SAMD9 (sterile alpha motif domain containing 9)
Diseases named in the same sentence as SAMD9 in open-access papers (continued):
Sharing a sentence is not in itself a finding about the gene and the disease.
leukemia (3 papers, 2022 to 2024). A malignant (clonal) hematologic disorder, involving hematopoietic stem cells and characterized by the presence of primitive or atypical myeloid or lymphoid cells in the bone marrow and the blood. "In some cases, as in the patient with a SAMD9 mutation and (progressive) dysplasia, it has also accelerated the route to HSCT, to prevent progression to MDS or leukemia." (PMID 35572556, 2022).
Pancytopenia (3 papers, 2018 to 2025). An abnormal reduction in numbers of all blood cell types (red blood cells, white blood cells, and platelets). "Germline gain-of-function (GOF) mutations, therefore, increase SAMD9 or SAMD9L antiproliferative effect causing pancytopenia, BMF and generally restricted growth and/or specific organ hypoplasia in non-hematopoietic tissues in an autosomal dominant fashion." (PMID 33802366, 2021). "Gain-of-function mutations in SAMD9 and SAMD9L, located on chromosome 7, enhance antiproliferative effects, leading to pancytopenia and restricted growth or organ hypoplasia in non-hematopoietic tissues." (PMID 40358701, 2025).
platelet disorders (3 papers, 2020 to 2024). "Moreover, MDS due to germline telomere biology disorders, SAMD9/SAMD9 mutations, GATA2 mutation and familial platelet disorders secondary to mutations in RUNX1, ETV6, or ANKRD26 may present across all ages." (PMID 33233642, 2020).
colon cancer (2 papers, 2007 to 2017). "SAMD9 regulates cell proliferation and apoptosis, and decreases tumor growth of colon cancer cell line in immune deficient mice." (PMID 17407603, 2007). "Over expression of SAMD9 in the colon cancer cell line, SW480, reduces the volume of tumors formed when transplanted into immune-deficient mice." (PMID 17407603, 2007). "Expression of SAMD9 was lower in 20% cases of breast cancer and 35% cases of colon cancer than in the normal control tissues." (PMID 17407603, 2007).
esophageal squamous cell carcinoma (2 papers, 2023). Esophageal squamous cell carcinoma (ESCC) is a type of esophageal carcinoma (EC) that can affect any part of the esophagus, but is usually located in the upper or middle third. "This work demonstrates the clinical and functional role of SAMD9 in esophageal squamous cell carcinoma (ESCC)." (PMID 36757050, 2023). "Sterile alpha motif domain-containing protein 9 (SAMD9) promotes EMT and metastasis of esophageal squamous cell carcinoma by stimulating MYH9-mediated GSK3β/β-catenin signalling." (PMID 37875476, 2023).
normophosphatemic familial tumoral calcinosis (2 papers, 2018 to 2021). "SAMD9 was initially identified as a tumor suppressor whose loss-of-function mutations in humans cause normophosphatemic familial tumoral calcinosis (NFTC)." (PMID 29447249, 2018).
astrocytoma (1 paper, 2021). "Patients with high expressions of SAMD9 were more concentrated in the astrocytoma than oligodendrocyte type." (PMID 33936093, 2021).
autoimmune disease (1 paper, 2021). A disorder resulting from loss of function or tissue destruction of an organ or multiple organs, arising from humoral or cellular immune responses of the individual to their own tissue constituents. "SAMD9 expression levels maybe a robust index for the evaluation of the degree of the immune response, deleterious mutations of SAMD9 is the cause of some autoimmune diseases and cancers." (PMID 33936093, 2021).
Cerebellar atrophy (1 paper, 2018). Cerebellar atrophy is defined as a cerebellum with initially normal structures, in a posterior fossa with normal size, which displays enlarged fissures (interfolial spaces) in comparison to the foliae secondary to loss of tissue. "SAMD9L mutations have been reported in a few families with balance problems and nystagmus due to cerebellar atrophy, and may lead to similar hematological disease as seen in SAMD9 mutation carriers, from early childhood to adult years." (PMID 29535429, 2018). "However, besides the similar hematologic phenotype, it remains elusive why the mutations in SAMD9L result in cerebellar atrophy while mutations in SAMD9 are associated with complex multi-organ defects." (PMID 29535429, 2018).
hypospadias (1 paper, 2024). Hypospadias is the displacement of the urethral meatus on the ventrum of the penis. "The presence of endocrine disease, including hypospadias, and the absence of specific SAMD9 variants in pregnancy loss and growth restriction cohorts underscore the syndrome’s complexity and potential underdiagnosis." (PMID 38539345, 2024).
lymphopenia (1 paper, 2022). Reduction in the number of lymphocytes. "Genomic and phenotypic analyses recapitulated many of the hematopoietic cellular phenotypes observed in patients with SAMD9 or SAMD9L mutations, including lymphopenia, and pinpointed TGF-β as a potential targetable pathway." (PMID 36074606, 2022).
papilloma (1 paper, 2016). A benign epithelial neoplasm that projects above the surrounding epithelial surface and consists of villous or arborescent outgrowths of fibrovascular stroma. "It is certainly plausible that SAMD9 is an important molecular target, which may mediate the responsiveness of papilloma growth to IFN treatment." (PMID 26901061, 2016).
psoriasis (1 paper, 2025). An autoimmune condition characterized by red, well-delineated plaques with silvery scales that are usually on the extensor surfaces and scalp. "A total of 5 genes (DEFB103A, OAS3, OASL, SAMD9, STAT1) were co-identified as characteristic genes in psoriasis progression and treatment." (PMID 40560938, 2025). "In summary, the study identified a series of characteristic genes (DEFB103A, IFI16, OAS3, OASL, SAMD9, STAT1, etc.)that are highly related to the occurrence, treatment of psoriasis." (PMID 40560938, 2025).
rheumatoid arthritis (1 paper, 2023). A chronic, systemic autoimmune disorder characterized by inflammation in the synovial membranes and articular surfaces. "A previous study revealed that SAMD9 could influence cytokine expression and T cell proliferation and act as an anti‐inflammatory factor in rheumatoid arthritis." (PMID 37904675, 2023).
Sepsis (1 paper, 2022). Sepsis is defined as life-threatening organ dysfunction caused by a dysregulated host response to infection. "Our findings revealed three novel low-frequency variants associated with reduced 28-day survival among sepsis patients: one in SAMD9 (the p.Ala1556Thr exonic variant), one intergenic to SLC5A12\FIBIN, and another intergenic to LINC00378\MIR3169." (PMID 36335405, 2022). "Because the T allele of rs34896991 predicts a missense change in SAMD9, this allele could act as a defective variant explaining its association with increased mortality risk among the patients with sepsis." (PMID 36335405, 2022). "A final assessment of transcriptomic array data from independent sepsis survivors and non-survivors from GSE65682 did not validate the association of SAMD9 expression with sepsis survival (log fold change: − 0.01 p value: 0.688)." (PMID 36335405, 2022). "While information was only available for coding genes, an upregulation of SAMD9 expression in non-surviving sepsis patients was observed in GSE54514 (log fold change: 0.545 adjusted FDR p value: 2.18 × 10−3)." (PMID 36335405, 2022).
small cell lung carcinoma (1 paper, 2017). Small cell lung cancer (SCLC) is a highly aggressive malignant neoplasm, accounting for 10-15% of lung cancer cases, characterized byrapid growth, and early metastasis. "SAMD9 and SAMD9L are likely to act as growth suppressors, and overexpression of SAMD9 suppresses tumor progression in non–small cell lung cancer cells." (PMID 28346228, 2017).
tumor (26 papers, 2007 to 2025). "The SAMD9 gene is down-regulated in a variety of neoplasms and deleteriously mutated in normophosphatemic familial tumoral calcinosis." (PMID 26901061, 2016). "For example, SAMD9, the gene most significantly upregulated by clorgyline, is repressed in a variety of neoplasms associated with beta-catenin stabilization." (PMID 19691856, 2009). "Spatial mapping revealed that SAMD9 was predominantly distributed in regions of microvessel proliferation and peri-necrotic niches, where SAMD9-positive tumor cells actively interacted with vascular cells and tumor-associated macrophages (TAMs)." (PMID 41331572, 2025). "Interestingly, upregulated genes MYCT1, and SAMD9 have been implicated as tumor suppressors in other cancers such as hematologic malignancies." (PMID 38589567, 2024). "SAMD9-positive tumor cells localize to peri-necrotic and hypervascular niches, actively engaging with TAMs and vascular cells, and their expression predicts poor survival and resistance to anti-angiogenic and anti-PD-1 therapies." (PMID 41331572, 2025). "This suggests that SAMD9 is a tumor microenvironment-responsive gene, induced by both hypoxic stress and TAM-derived inflammatory signals." (PMID 41331572, 2025). "This role in immune modulation was further supported by a significant correlation between SAMD9 and canonical immune checkpoint molecules in the TCGA bulk tissue transcriptome, suggesting its potential role in tumor immune escape." (PMID 41331572, 2025). "Our investigation into tumor-host interactions revealed that SAMD9-positive tumor cells are in close proximity to both M1 and M2 TAMs." (PMID 41331572, 2025). "SAMD9 expression was significantly elevated in tumor cells co-cultured with THP-1-derived TAMs compared to those exposed to untreated THP-1 cells." (PMID 41331572, 2025). "Validation using an additional spatial transcriptiomics atlas corroborated that SAMD9-expressing tumor cells reside in niches characterized by intense intercellular interactions with TAMs and vascular cells." (PMID 41331572, 2025). "Consistently, the subcutaneous xenograft model results also showed that SAMD9 overexpression significantly enhanced the ability of tumor formation and tumor growth." (PMID 36757050, 2023). "Further, the authors demonstrated that silencing SAMD9 inhibited lung metastasis and tumor formation in vivo." (PMID 36757050, 2023). "In contrast, silencing SAMD9 dramatically suppressed tumor formation and growth in nude mice compared to that of the vector control." (PMID 36757050, 2023). "But, the tumor‐promoting mechanism of SAMD9 in ESCC is unclear, and the correlation between SAMD9 and postoperative recurrence in ESCC has not been reported." (PMID 36757050, 2023). "Three over-expressed, amplified, and mutated molecules were identified as tumor antigens, i.e., KDR, COL1A2, and SAMD9, and found to be associated with unfavorable prognosis." (PMID 34815785, 2021). "The patients with high KDR, PDGFRA, LRP1, COL1A2, and SAMD9 expression had shorter OS (log-rank test, P < 0.05), indicating that tumor antigens were critical for the progression of diffuse gliomas." (PMID 34815785, 2021). "Human SAMD9, a tumor suppressor and a restriction factor for poxviruses in cell lines, is antagonized by two classes of poxvirus proteins, represented by vaccinia virus (VACV) K1 and C7." (PMID 29447249, 2018). "Surprisingly, germline variants in SAMD9 or SAMD9L were present in 17% of primary MDS patients, and these variants were routinely lost in the tumor cells by chromosomal deletions (e.g., monosomy 7) or copy number neutral loss of heterozygosity (CN-LOH)." (PMID 29146900, 2017). "Using real-time quantitative PCR and microarray analysis they found that SAMD9 gene was upregulated in tumor cells treated with the virus and the SAMD9 messenger ribonucleic acid (mRNA) was upregulated in a time and dose-dependent manner." (PMID 29164063, 2017).
tumor (continued). "In contrast, reduced SAMD9 expression has been reported in several tumor tissues, cisplatin chemoresistance, and normophosphatemic familial tumoral calcinosis." (PMID 28346228, 2017). "Our in vitro data suggests SAMD9 regulates cell proliferation rate in both normal and tumor cell lines." (PMID 17407603, 2007). "To verify the role of SAMD9 on neoplasia, we performed experiments when the expression of SAMD9 was lowered using RNA interference." (PMID 17407603, 2007). "For instance, SAMD9 overexpression restrains tumor genesis and progression of NSCLC." (PMID 40936767, 2025). "In the metastasis group, the top shared upregulated genes were cancer-related with diverse functions, including tumor suppressors (SAMD9 and SEMA3B) and genes involved in growth, survival, cytoskeletal dynamics, motility, invasion, and metastasis (RHOBTB3, CYP24A1 and PTGS2)." (PMID 40605119, 2025). "Our observation of marked SAMD9 expression in the peri-necrosis region and its upregulation under hypoxia suggests it may facilitate aggressive tumor expansion and pseudopalisade organization." (PMID 41331572, 2025). "Additionally, the positive regulation of vimentin and β‐catenin expression, and the negative regulation of E‐cadherin expression by SAMD9 were demonstrated in xenograft tumor tissues by IF analysis." (PMID 36757050, 2023). "The knockouts in tumor cell lines from various tissues and the normal human foreskin fibroblasts showed that both SAMD9 and SAMD9L, when sufficiently expressed, could inhibit vK1L-C7L- replication." (PMID 29447249, 2018). "SAMD9 is a potential tumor suppressor, and is down-regulated in a variety of neoplasms." (PMID 26901061, 2016). "It was found to be associated with the absence of functional SAMD9, a putative tumor suppressor and anti-inflammatory protein." (PMID 21854601, 2011). "While conclusions in their manuscript on the species conservation of SAMD9 are incorrect, the occurrence of soft tissue lesions in this inherited condition supports our notion that SAMD9 plays an important role in cell processes that are important in neoplasia." (PMID 17407603, 2007). "Sterile Alpha Motif Domain-containing 9 (SAMD9) and its paralog SAMD9-like (SAMD9L) are antiviral factors and tumor suppressors." (PMID 40291743, 2025). "Our findings indicate that SAMD9 is co-expressed with these immune inhibitory molecules (PD-L1, IDO1) within immunosuppressive tumor subset, potentially attributed to sustained IFN stimulation." (PMID 41331572, 2025). "Overexpression of SAMD9 promotes tumor stemness, angiogenesis, and EMT, while downregulation of SAMD9 reduced these phenotypes." (PMID 36757050, 2023). "Based on immunohistochemistry (IHC) scoring of the primary tumor, 123 ESCC patients were assigned to high and low SAMD9 expression groups." (PMID 36757050, 2023). "Finally, to determine whether the level of SAMD9 is directly associated with ESCC recurrence, when the mean tumor volume reached ∼45 mm3, mice inoculated with ECA109‐vector and ECA109‐SAMD9 or TE1‐scramble and TE1‐shRNA of SAMD9 cells began receiving CDDP (cis‐diaminedichloroplatinum) treatment." (PMID 36757050, 2023). "Among the INFA response-enriched genes, SAMD9, CXCL10 and CXCL11 genes overlapped in the exosomes; tumor tissue overlapped from the core enrichment genes." (PMID 36230645, 2022). "Exosomal mRNA analysis showed that CXCL10, CXCL11 and SAMD9 were highly expressed in CRC patients with liver metastasis, which was validated by tumor RNA sequencing using GSEA." (PMID 36230645, 2022). "SAMD9 and SAMD9L are expressed ubiquitously in human tissues, but they are expression at lower levels in neoplasia." (PMID 17407603, 2007). "Mouse is one of the mammalian species that have lost SAMD9 gene, and a previous study suggested that mouse SAMD9L was not a functional paralog of human SAMD9 in terms of the tumor suppressor function." (PMID 29447249, 2018).
tumor (continued). "Over-expression of SAMD9 in SW480 cells reduced the volume of tumors that formed in nude mice and NOD-SCID mice, while the decreased expression in SW480 cells increased the tumor volume formed in nude mice suggesting a role suppressing the neoplastic phenotype." (PMID 17407603, 2007). "Furthermore, when we compare the differentially expressed genes between KPT-330 treated cells as compared to cells with TRIP13 suppression, we find several potential tumor suppressors such as MYCT1 and SAMD9, a gene having antiproliferative properties, whose expression increases." (PMID 38589567, 2024). "The partial correlation between the SAMD9 expression level and the six immune cell types: B cell, CD4 T cell, CD8 T cell, neutrophils, macrophages and dendritic cells in the tumor microenvironment was systematically estimated based on the Tumor Immune Estimation Resource (TIMER) algorithm." (PMID 33936093, 2021).
infection (22 papers, 2016 to 2025). The state of being infected such as from the introduction of a foreign agent such as serum, vaccine, antigenic substance or organism. "In either case, wildtype MYXV infection significantly reduced the amount of SAMD9 associated with dsDNA compared with that from ΔM062R infection." (PMID 36103568, 2022). "SAMD9 has further been shown to associate with stress granules induced by infection with host range deletion mutants." (PMID 26901061, 2016). "However, during ΔM062R infection, SAMD9 can be detected abundantly associated with the viral factories." (PMID 36103568, 2022). "The M062R gene product is essential for MYXV infection in almost all cells tested from different mammalian species and specifically inhibits the function of host Sterile αMotif Domain-containing 9 (SAMD9), as M062R-null (ΔM062R) MYXV causes abortive infection in a SAMD9-dependent manner." (PMID 36103568, 2022). "We have reported previously that the infection defect by ΔM062R was due to its inability to overcome host SAMD9 function." (PMID 36103568, 2022). "We thus concluded that ΔM062R infection stimulated a unique pro-inflammatory state that is cGAS-dependent and also regulated by SAMD9." (PMID 36103568, 2022). "We found that the replication-defective ΔM062R activated host DNA sensing pathway during infection in a cGAS-dependent fashion and that knocking down SAMD9 expression attenuated proinflammatory responses." (PMID 36103568, 2022). "IFI44, ISG15, MX1, RSAD2, SAMD9 and TNFSF10 were chosen as they are infection-associated genes that show lower expression levels in Holstein infected cells compared to Sahiwal cells." (PMID 35061738, 2022). "AVGs accumulation was abolished and abortive infection was rescued in ΔC7L/K1L in SAMD9-depleted cells, suggesting that C7L/K1L antagonize SAMD9 host protein antiviral function." (PMID 31681621, 2019). "Here, we show that SAMD9L functions similarly to SAMD9 as a restriction factor and that the two paralogs form a critical host barrier that poxviruses must overcome to establish infection." (PMID 29447249, 2018). "Instead, SAMD9 determines the organization of AVGs formed during infection with M062R-null MYXV and the VACV C7L and K1L double-knockout virus." (PMID 27314378, 2016). "Studies of SAMD9/L from two different mammalian species and the SAMD9/L inhibitors from diverse mammalian poxviruses revealed some host species-specific difference in SAMD9/L, which could serve as a barrier for cross-species poxvirus infection." (PMID 29447249, 2018). "In fact, SAMD9 and SAMD9L are host restriction factors activated as a defensive mechanism in response to infection with viruses such as vaccinia, myxoma, and rhinovirus." (PMID 36074606, 2022). "The up-regulated TF ZFHX3 targets seven genes in module AD_M25, where two genes OAS1 and RSAD2 are detected in infection pathways, and the other five genes FAM122B, SAMD9, TRIM21, USP18 and IFIT3 are also known to be related to infectious disease." (PMID 30598117, 2018). "Even though translation shutdown is thought to occur during infection with VACV-C7LK1L-DKO, SAMD9-driven formation of AVGs in M062R-null MYXV infection does not necessarily result in the complete shutdown of translation (unpublished data by Li, Nounamo, and Liu)." (PMID 27314378, 2016).